INS (insulin)
Diseases named in the same sentence as INS in open-access papers (continued):
Sharing a sentence is not in itself a finding about the gene and the disease.
Insulin resistance (continued). "The fetal insulin hypothesis also proposes a relationship between inherited insulin resistance and altered growth mediated by insulin." (PMID 27087404, 2016). "Additionally, the ameliorated insulin resistance also improved the liver insulin sensitivity (Akt activation)." (PMID 27242912, 2016). "Therefore, the upregulation of miR-96 provokes an impairment of insulin signaling and glycogen synthesis in hepatocytes through the repression of INSR and IRS-1, and that miR-96 is a causal factor for SFA-induced hepatic insulin resistance." (PMID 28036389, 2016). "Significant differences between cases and controls were noted for mean BMI (P <0.001), free testosterone (P = 0.009), bioactive testosterone (P = 0.004), free androgen index (FAI; P = 0.015), fasting insulin (P <0.001), and the insulin resistance index HOMA-IR (P <0.001)." (PMID 27846231, 2016). "Comorbid metabolic disturbances aggravate the burden of depressive illness, in part by sharing common risk factors and pathophysiological pathways, since impaired insulin signaling and insulin resistance have been documented to play an important role in the pathogenesis of MDD." (PMID 26801406, 2016). "Thus, we evaluated the HOMA-IR, a useful index for assessing insulin resistance, insulin sensitivity, and β-cell function." (PMID 27869712, 2016). "Importantly, cerebral insulin resistance developed in the aged APN-KO mice with attenuated AMPK activation and impaired insulin signaling which was an underlying mechanism of AD pathogenesis." (PMID 27884163, 2016). "Given the involvement of these intermediates in inflammatory cytokine production and decreased GLUT4 translocation, these data suggest that insulin resistance in T1D elicits a shift toward the intramyocellular accumulation of insulin desensitizing, pro-inflammatory metabolites." (PMID 27197730, 2016). "It indicates that aliskiren may stimulate glucose utilization and increase insulin sensitivity in skeletal muscle, contributing to the improvement of systemic insulin resistance and reduction in serum glucose levels in HFD-fed mice." (PMID 26732252, 2016). "Moreover, 3–10-fold increases in Th17 cells were demonstrated in adipose tissue from obese patients with insulin resistance, when compared to obese insulin-sensitive or lean patients." (PMID 27212806, 2016). "Furthermore, we found that there was an interaction between SLC47A1 rs2289669 and SLC22A1 rs594709, which affected the blood glucose, insulin level, insulin resistance improvement, and blood lipid after metformin treatment." (PMID 26977146, 2016). "Poor insulin sensitivity indicates insulin resistance and is strongly related to obesity." (PMID 26942930, 2016). "However, the development of insulin resistance in obesity raises the question of how tumors utilize increased levels of circulating insulin in an insulin-resistant environment, a question I return to later in this article." (PMID 27604692, 2016). "Furthermore, BGE increased fasting insulin/glucose ratio, an index of insulin resistance, in a dose-dependent manner, which was notably reduced by MLDS treatment." (PMID 26751692, 2016). "Increased triglyceride levels in response to high-fructose diet could have resulted in insulin resistance by reducing the insulin signaling pathway." (PMID 28035952, 2016). "It has been well documented that systemic administration of ghrelin or endogenous ghrelin could restrict glucose-induced insulin release and deteriorate glucose tolerance in vivo and in vivo, which leads to insulin resistance, indirectly take part in obesity." (PMID 27240398, 2016). "This supports a model in which HFD causes selective insulin resistance in fat and that adipose tissue glucose uptake and DNL is linked to an extra-hepatic insulin-sensitizing signal that may be targeted early in obesity." (PMID 27098609, 2016).
Insulin resistance (continued). "Moreover, an oral glucose tolerance test and insulin tolerance test revealed that cold stress exacerbated the glucose intolerance and insulin resistance apparent in the MetS group in a manner sensitive to RU486." (PMID 27110688, 2016). "Of the various conventional anti-diabetic agents, thiazolidine derivatives are effective for improving insulin resistance by enhancing insulin sensitivity in peripheral tissues, but need to be administered with caution because of possible adverse effects such as worsening of edema and heart failure." (PMID 27044332, 2016). "Based on these previous findings, we hypothesized that inositol could be effective in improving insulin sensitivity in children with insulin resistance." (PMID 27882052, 2016). "However, there was a significant group by insulin AUC interaction (P < .05 corrected with familywise error), suggesting that the relationship between insulin resistance and white matter microstructure differed in PCOS and control groups." (PMID 26574952, 2016). "Conversely, glucose-6-phosphatase is insensitive to insulin in insulin resistance." (PMID 27653524, 2016). "This increase may be related to increased insulin resistance and higher demand for insulin in T1D and T2D patients." (PMID 27276680, 2016). "Thus, our observations cannot be attributed to consequences secondary to the pathological state that parallels most models of insulin resistance and hence likely reflect physiological adaptive responses to the very early insulin-resistant state." (PMID 26864436, 2016). "Using sodium stibogluconate we tested the hypothesis that SHP‐1 inhibition leads to improvement of insulin sensitivity in a mouse model of high‐fat diet (HFD) induced insulin resistance." (PMID 27047746, 2016). "Since the liver is the major site of IGF-1 production, when steatosis develops lowering insulin sensitivity, the severity of steatosis at different stages of insulin resistance and metabolic syndrome seems to be correlated with worsened circulating IGF-1 levels." (PMID 26733412, 2016). "Testosterone inhibited the insulin signaling in liver, thus increased insulin resistance." (PMID 27941939, 2016). "In contrast, vitamin D supplementation in insulin-resistant women has been reported to reduce insulin resistance when endpoint 25(OH)D concentrations were equal to or exceeded 80 nmol/L, suggesting that a potentially higher physiological limit of 25(OH)D is required to influence glycemic control." (PMID 27754361, 2016). "Some data suggest that inactivity-induced insulin resistance is primarily linked to impaired peripheral insulin action (i.e., in the muscle) rather than an inability to shut down endogenous glucose production." (PMID 27376322, 2016). "Additionally, the brains from Alzheimer's patients show characteristic signs of insulin resistance and the insulin sensitizing drugs, thiazolidinediones, have been shown to improve memory in both mice and human patients." (PMID 28066166, 2016). "Impaired hippocampal insulin signaling in our study is evident by the decrease in the Y1222 pIRS1 and the increase in serine 307 and 636/639 pIRS1, which has also been reported in animal models of insulin resistance and obesity." (PMID 27676071, 2016). "The effects of Z-551 were examined in wild type mice on HFD and it could suppress body weight gain, ameliorated insulin resistance and abnormal lipid metabolism, significantly reducing the plasma levels of glucose, FFAs, insulin and leptin." (PMID 27483259, 2016). "Next, we tested whether muscle-specific ERRγ activation protected against insulin resistance and glucose intolerance by performing insulin (ITT) and glucose (GTT) tolerance tests." (PMID 27220353, 2016).
Insulin resistance (continued). "The objective of this study was to determine which measure — MVPA or TAC/d —is more strongly associated with 2 markers of insulin resistance commonly used in epidemiological research — HOMA-IR and the quantitative insulin sensitivity check index (QUICKI) — in a representative sample of US adults." (PMID 27763832, 2016). "WT mice fed the Western diet developed overt T2DM, with fasting glucose levels of 200 mg/dl, despite increased insulin levels, and HOMA (homeostatic model assessment)-insulin resistance higher than 15, whereas caspase-2-deficient mice maintained normal glucose metabolism." (PMID 26890135, 2016). "First, elevated plasma TG provokes ectopic lipid storage in insulin targeted organs, such as the liver and skeletal muscle, and induces the onset of insulin resistance by interrupting the insulin signaling pathway, activating oxidative stress and endoplasmic reticulum stress." (PMID 27034649, 2016). "Insulin resistance (or reduced insulin sensitivity) is characterized by suboptimal biological responses of the liver, skeletal muscle and adipose tissue to normal amounts of insulin secreted." (PMID 27770799, 2016). "Bilateral CB denervation prevents diet-induced insulin resistance and hypertension, suggesting that insulin-induced CB chemosensory excitation is responsible for the increased sympathetic outflow, creating a positive feedback, which results in severe insulin resistance and hypertension." (PMID 26920146, 2016). "Both have been shown to inhibit insulin signaling, inducing an insulin resistance state that may affect other organs." (PMID 28933394, 2016). "To wit, that below a certain threshold, there is a monotonic relation between obesity (as measured by BMI) or BW gain and insulin resistance; but above this level, BW gain has exerted its maximum effect, and there is no further relation between degrees of BW gain and degree of insulin resistance." (PMID 26728312, 2016). "For ectopic fats, while some studies claim that increased triglycerides in muscle may lead to insulin resistance, others suggest increased triglycerides during exercises correlate with insulin sensitivity." (PMID 27180971, 2016). "Combined evaluation of fasting insulin and glucose concentrations is likely to offer better background on insulin resistance among the studied subjects, and will clarify whether insulin or glucose level has more impact on cardiac autonomic modulations." (PMID 27441373, 2016). "Our findings instead suggest that low doses of rapamycin, by specifically inhibiting mTORC1, could be beneficial in pathological conditions where an excessive insulin secretion and signalling is present, such as in insulin resistance." (PMID 26563389, 2016). "Insulin resistance (IR) is a physiological condition in which a given concentration of insulin produces a less-than-expected biological effect, because cells fail to respond to the normal actions of the hormone insulin, leading to dysfunctions of glucose transfer and utilization." (PMID 26770659, 2016). "Furthermore, a study showed that the plasma levels of glucose, leptin, insulin, total cholesterol, and triglyceride were lowered in high-fat diet mice treated with Ergostatrien-3β-ol from A. camphorata, and insulin resistance was also attenuated in these mice." (PMID 27047382, 2016). "Because the results of Studies I and II showed that exposure to CAP for 30 days impairs insulin signaling in multiple tissues, we asked whether a briefer exposure would induce cardiovascular insulin resistance." (PMID 27128347, 2016). "In summary, we found under insulin resistant conditions, autophagy activity in podocytes is downregulated in vitro, and activation of autophagy could prevent insulin resistance induced podocyte injury." (PMID 27077005, 2016).
Insulin resistance (continued). "Pregnancy is typically accompanied by physiological insulin resistance that begins the second trimester and progresses through the third trimester, leading to an increase in maternal insulin secretion to maintain blood glucose levels as a consequence of adaptive pancreatic beta-cell proliferation." (PMID 27793207, 2016). "The same authors demonstrated that consumption of the DASH diet by pregnant women with GDM had beneficial effects on fasting plasma glucose, serum insulin levels, Homeostasis Model of Assessment-Insulin Resistance score, plasma total antioxidant capacity, and total glutathione levels." (PMID 27338455, 2016). "In addition, it is well known that during the compensated stage of type 2 diabetes, the circulatory insulin level of subjects is enhanced due to hyperglycemia stimuli and insulin resistance." (PMID 27127795, 2016). "However, many people with insulin resistance maintain normal glycaemia due to compensatory rises in pancreatic insulin secretion." (PMID 27111219, 2016). "Upon binding to the complex of CD14 and toll-like receptor 4 at the surface of innate immune cells, LPS can trigger the secretion of proinflammatory cytokines, which eventually impairs insulin sensitivity and induces insulin resistance-related metabolic disorders." (PMID 27036035, 2016). "The traditional concept has been that the initial insult is insulin resistance compensated by hyperinsulinemia, related to liver dysfunction (due to iron deposition), that may interfere with insulin’s ability to suppress hepatic glucose uptake." (PMID 27872738, 2016). "Based on experiments in non-diabetic mice both in vivo and in muscle biopsies, and in L6 cells exposed to the db/db medium and to serum from insulin resistant humans, it has been hypothesized that jejunal factor/s induce insulin resistance." (PMID 27149630, 2016). "The gold standard to evaluate insulin resistance is the euglycemic insulin clamp technique." (PMID 27471550, 2016). "Lower postprandial insulin response is considered beneficial because this would be less demanding for the pancreatic β-cells and could play a role in preventing insulin resistance." (PMID 27749919, 2016). "Genome-wide association studies (GWAS) and exome sequencing have identified a large number of genes linked to susceptibility to T2D, helping to understand the pathogenesis of T2D and the genes that influence pancreatic beta-cell function/insulin secretion and insulin resistance." (PMID 27383215, 2016). "HUA may indirectly inhibit insulin signaling and induce insulin resistance via oxidative stress in cardiomyocytes." (PMID 26836389, 2016). "In addition to the lipotoxicity, insulin resistance is another hallmark of NAFLD, which is accompanied by reduced insulin sensitivity in the liver and increased circulating insulin level." (PMID 27104558, 2016). "Despite the importance of insulin sensitivity to metabolic health, the mechanisms that induce insulin resistance remain unclear." (PMID 27376324, 2016). "Insulin was increased in MetS rats and there was insulin resistance indicated by HOMA-IR." (PMID 28036029, 2016). "In addition to increased glucose levels, T2DM is also characterized by a condition known as insulin resistance (IR), which is defined as a reduction of sensitivity and/or reactivity of the target cells to plasmatic insulin." (PMID 26839569, 2016). "Even though it is not still clear whether BCAAs are causative factors in the development of IR, or whether they are biomarkers of impaired insulin action, the involvement of nutrient signaling in insulin resistance has emerged." (PMID 27376324, 2016). "Meanwhile, insulin resistance could be involved in salt-induced obesity, and further studies will be needed to reveal the relationship between ghrelin and insulin during high-salt diet." (PMID 27240398, 2016).
Insulin resistance (continued). "Another limitation of this study was the lack of a more thoroughly analysis of the insulin signaling to determine if the glucose intolerance reported here is associated with insulin resistance." (PMID 27538526, 2016). "Patients with insulin resistance have raised blood insulin levels." (PMID 27653524, 2016). "Further, molecular markers of insulin resistance co-localize with tau inclusions in AD brain, suggesting that impaired insulin signaling may be a key factor in the AD pathophysiological cascade." (PMID 26858121, 2016). "Metformin and thiazolidinediones (TZD) (troglitazone, rosiglitazone, pioglitazone) are standard medications for treatment of DM2 via decreasing insulin resistance, improving insulin sensitivity in peripheral tissues, reducing free androgen levels and facilitating normal regular menses and pregnancy." (PMID 28331909, 2016). "Furthermore, insulin resistance and fasting insulin level formed a strong relationship with NAFLD, independent of HT." (PMID 27166773, 2016). "The difference between the role of IRS1 and IRS2 in insulin signaling cascade could account for the existence of selective insulin resistance in liver." (PMID 27247938, 2016). "For T2DM, there is a higher concentration of blood insulin than normal due to insulin resistance." (PMID 27893760, 2016). "We treated rats with insulin alone or in combination with human chorionic gonadotropin (hCG) and showed that peripheral insulin resistance and hyperandrogenism alter uterine morphology, cell phenotype, and cell function, especially in glandular epithelial cells." (PMID 27461373, 2016). "In obese volunteers, insulin, the homeostatic model assessment of insulin resistance (HOMA-IR), leptin, the leptin/adiponectin ratio, and pro-inflammatory chemokines growth-related oncogene and macrophage-derived chemokine were significantly higher compared to non-obese submariners." (PMID 26867201, 2016). "However, the indexes of β-cell function and insulin resistance were calculated based on C-peptide instead of insulin, which ensured the accuracy of results as far as possible." (PMID 26649318, 2016). "Early intensive insulin therapy could effectively reduce glucotoxicity and lipotoxicity, protect islet function, and alleviate insulin resistance in patients with newly diagnosed T2DM." (PMID 27881128, 2016). "We found that the extracts blocked the increase of fasting blood glucose, serum triglyceride (TG), insulin, leptin, and liver lipid levels and prevented the development of glucose tolerance impairment and insulin resistance in the C57BL/6 mice induced by a high-fat diet." (PMID 27088095, 2016). "There were clinical and biological evidences of insulin resistance with acanthosis nigricans in the axillae and cervical regions, increased fasting plasma insulin (89.4 mUI/L (normal range: 6.5–29.1) and homeostasis model assessment of insulin resistance (HOMA-IR at 29)." (PMID 27120622, 2016). "Unlike “common” insulin resistance, this is associated with elevated plasma levels of the insulin-sensitising, adipose-derived protein adiponectin." (PMID 26888756, 2016). "Adiponectin is an insulin sensitizer, and reduced adiponectin levels and/or ratios of HMW/LMW are linked to insulin resistance and metabolic syndrome." (PMID 26993044, 2016). "In liver, adiponectin protein attenuates insulin resistance by increasing insulin sensitivity." (PMID 26965314, 2016). "To explore the effect of exendin-4 on macrophage-secreted inflammatory cytokines mediated insulin resistance, we tested the insulin-stimulated glucose uptake using 3T3-L1 adipocytes which were incubated with LPS or exendin-4-treated macrophage CM from RAW264 cells or mouse peritoneal macrophages." (PMID 27878229, 2016). "Moreover, in obese subjects, small fat cells predominate in individuals with abnormal insulin resistance, whereas larger fat cells are more numerous in insulin-sensitive subjects." (PMID 26770660, 2016).